ID1 (inhibitor of DNA binding 1)
Diseases named in the same sentence as ID1 in open-access papers (continued):
Sharing a sentence is not in itself a finding about the gene and the disease.
tumor (continued). "We have previously shown that Id1 cooperates with oncogenic Ras in mammary tumourigenesis and metastasis in vivo, but the role for Id1 overexpression alone in mammary development and neoplasia has not been investigated." (PMID 20689821, 2010). "In addition to its role in TGFβ-mediated Id1 repression, ATF3 also functions to suppress tumour growth." (PMID 20565867, 2010). "These previous studies suggested that due to ID-1 suppression, TSP-1 expression might be lost with tumour advancement, resulting in drastic tumour angiogenesis that accelerates tumour advancement." (PMID 19002177, 2008). "It has been reported that Id-1 did not have an activity in normal tissue in some tumours, but was only expressed in cancer cells." (PMID 19014499, 2008). "Although Id-1 is thought to play a role in tumorigenesis and can be a new therapeutic target, it is not clear how it affects molecular mechanisms in various tumours." (PMID 19014499, 2008). "We have shown recently that utilization of EPCs is most prominent early in tumor development and that antibody ablation specifically of the EPC population mimics the phenotype described in the Id1-/-mice with abnormal tumor vasculature and delayed tumor growth." (PMID 18092003, 2007). "Ablation of p21 in the Id1 mutant background (through genetic manipulation) completely corrects the differentiation defect of HSCs restoring a normal EPC population in the BM and in the peripheral blood and rescuing normal tumor angiogenesis." (PMID 18092003, 2007). "The same pattern of Id1 expressing BM cells was observed 4 days after tumor implantation (data not shown)." (PMID 18092003, 2007). "Indeed, several of the identified genes in our study are reported to be involved in angiogenesis, tumor angiogenesis and arteriogenesis, i.e. IL-8, ET-1, CARP, HPTPη, ID1, MGSA, SMAD7, HO-1, RHOB, PTHLH, SERPINH1/HSP47, JAG1, GNA13 and TEAD4." (PMID 16594992, 2006). "Still, when adjusted for other strong prognostic factors in this patient series, like tumour thickness and others, ID1 expression had no independent prognostic significance in multivariate Cox analysis." (PMID 16189525, 2005). "The fact that id1 was not impacted by NICD loss and is down-regulated in ATL patients suggests that ID1 may have tumor suppressor functions in ATL cells that are currently undefined." (PMID 38791169, 2024). "However, comparisons from clinical samples and TCGA database between tumor samples and normal samples indicated that ID1 is lowly expressed, not highly expressed, in HCC." (PMID 37964494, 2024). "The tumor inhibition rate in BALB/c nude mice was approximately 50%, whereas that in C57BL/6J mice was more than 80%, indicating that ID1 expressing TAMs may destroy the T cell-mediated antitumor immune response." (PMID 37996458, 2023). "In lung cell, CCNDBP1 has been proposed to repress ID1 (inhibitor of DNA binding 1, HLH protein) expression, inactivate of PI3K/Akt signaling pathway and further suppress cell proliferation, migration, invasion and tumorigenesis, thus effecting as a tumor suppressor." (PMID 37058478, 2023). "Gene set enrichment analysis (GSEA) suggested that Id1 deletion in TAMs resulted in the inhibition of focal adhesion kinase (FAK) and Yes-associated protein (YAP) signaling pathways but not other tumor stemness associated signaling such as Notch, Wnt/β-catenin and Sonic hedgehog (SHH) pathway 29,30." (PMID 37996458, 2023). "We previously reported that JL5 decreases the expression of Id1 but not XIAP in tumor xenografts." (PMID 34563224, 2021). "In addition to activation of the ID1 pathway, a crosstalk between SMAD1 and NF-κB1 acting as a tumor inducer circuit, may provide a novel mechanism for SMAD1-mediated myelomagenesis." (PMID 34134766, 2021). "Indeed, ID-1 has a similar effect of apoptosis induction exerted on the CD-80 and CD-86 ligands on these tumor cells (data not shown), accordingly with previous results reported in literature." (PMID 32781690, 2020).
tumor (continued). "Therefore, we conclude that miR-199b-5p could suppress tumor angiogenesis by targeting ALK1 and the ALK1/Smad/Id1 signaling pathway may be involved in the mechanism." (PMID 32082362, 2019). "Id1, Id2 and Id3 may increase MMP gene expression, leading to tumor cell invasion." (PMID 28122577, 2017). "However, Id1 has not been previously involved in regulating the crosstalk between tumours and the host immune system at a systemic level and promoting tumour progression and metastasis via the suppression of myeloid cell differentiation." (PMID 25924227, 2015). "Although Id1, Id2 and Id3 were highly over-expressed in SCLC in our previous work, it is not known what exact roles they may play in SCLC cells and whether they can be used as a joint or separate treatment targets for tumor suppression." (PMID 25061504, 2014). "However, there was a more dramatic reduction of the tumor observed when co-treated with paclitaxel and cisplatin in the Id1-GFP-overexpressing group (Id1-OE+C/T, O4) (P < 0.0001) compared with the vector control (Id1-EV+C/T, P7) (P = 0.04)." (PMID 25344919, 2014). "As far as we know, the role of Id1 in EGCG-induced tumor inhibition has not been reported so far." (PMID 23900621, 2013). "While the majority of PDIC tumors were found to be entirely positive for Id1, we found two instances in which Id1 was regionally expressed; for example, present only in tumor cells along the invasive front of the PDIC, with the remainder of the tumor only having Id1 expression in endothelial cells." (PMID 23691228, 2013). "Firstly, the response rate (RR) achieved with the treatment seemed to be lower among patients showing a tumor Id1/Id3 co-expression compared to those showing no Id1/1d3 co-expression with a trend towards statistical significance using the MacNemar’s test, (RR = 50% vs 87.5%, respectively; p = 0.07)." (PMID 23311395, 2013). "The majority of PDICs were found to be entirely Id1+, suggesting that tumors arose from a single clone, consistent with the hypothesis that these tumors originated through a separate pathway or cell of origin to the other classes of RT2 tumor." (PMID 23691228, 2013). "However, for those patients with tumor samples showing an exclusive Id1 expression in the absence of Id3 expression, no impact of that expression on clinical outcomes was observed." (PMID 23311395, 2013). "A recent report showed that tumor could induce high expression of Id1 in EPCs derived from BM but not in other cells, suggesting that Id1 might be a key factor for EPCs." (PMID 23714001, 2013). "Moreover, mice lacking Id1/Id3 genes are resistant to tumour neoangiogenesis and tumour cells failed to grow and/or metastasize." (PMID 23555842, 2013). "Therefore, we suggest that Id1/3-PA7, as inhibitor of Id1 and Id3, could have the potential to be used as a new tool for targeted tumour therapy." (PMID 20842131, 2010). "In an examination of primary NPC tumours (T1, T2 and T3), which displayed strong, moderate, and weak expression of LMP1 respectively, we observed a positive correlation between expression of LMP1 and that of Id1, whereas expression of Foxo3a was inversely correlated with LMP1 expression." (PMID 20565867, 2010). "Moreover, flow cytometric analysis of tumor tissue showed a comparable number of infiltrating CD11b- VE-Cadherin+ cells in wild type and Id1-/-p21-/- mice (data not shown)." (PMID 18092003, 2007). "However, no significant relation was found between Id-1 expression and PI (tumour cell proliferation) or AI (tumour cell apoptosis) (P=0.47, 0.62, respectively)." (PMID 15026801, 2004).
tumor (continued). "Moreover, Id1 overexpression contributes to systemic immunosuppression by downregulating key molecules involved in dendritic cell differentiation and suppressing CD8+ T cell responses, creating an immunosuppressive macroenvironment that supports tumour growth and progression." (PMID 39676870, 2024). "Interestingly, we also compared their expression levels between tumor and normal tissues and found that the expressional changes were complex, especially significantly upregulated genes (CDKN2A, MYCN, PLK1, and TERT) and some downregulated signatures (AXL, ID1, and TLR3)." (PMID 35754848, 2022). "Therefore, our microarray analysis results fit well with the known effects of signaling pathways and genes on tumorigenesis, suggesting that the promotion of tumor development by C1QTNF6 might be mediated through regulation of Acute Phase Response signaling and ID1, BBC3, and DDIT3 gene expression." (PMID 34906149, 2021). "Furthermore, ectopic gene expression of EMT inducers and ID1 may not provide conclusive evidence of these concepts in a complex in vivo tumor setting." (PMID 25927844, 2014). "Additionally, the PFS analysis showed similar differences in favor of patients lacking Id1/Id3 co-expression in their tumor samples, although the limited number of patients included could have accounted for the lack of statistical significance observed." (PMID 23311395, 2013). "However, we could not exclude the possibility that Id1 reduces the tumor volume by inhibition of angiogenesis." (PMID 23714001, 2013). "As IL-6 is correlated with both Gleason grade of the individual cores and distant metastasis in our patient cohort, regardless of the Gleason score of the tumours, IL-6 might be one factor that could explain the partial rescue of the Id-1-induced phenotypes by recombinant TNF-β." (PMID 20010941, 2010). "In addition, no Id-1 expression was detected in the normal colon mucosa neighbouring the tumour." (PMID 19014499, 2008). "Using Id1f/f and Id1Lyz-KO mice, we demonstrated that depletion of Id1 in myeloid cells largely but not totally reversed the tumor inhibitory role of ML323 in MC38 s.c. model, indicating that ML323 works partly through Id1 in myeloid cells." (PMID 37996458, 2023). "Flow cytometry analysis of the tumour xenografts revealed an increase in GFP+/VEGFR1+ cells, but not the other subpopulations, in the Id1 group only." (PMID 28186102, 2017). "To investigate the potential role of Id-1 in NSCLC development, we firstly measured the expression of Id-1 in paired tumor tissues and matched adjacent noncancerous tissues from 96 patients with NSCLC using qRT-PCR." (PMID 29233161, 2017). "At 24 months of age, none of the wild-type mice developed a tumor, whereas 10 cases of ductal hyperplasia and two tumors were observed in a total of 69 MMTV-Id1 mice in which constitutive Id1 overexpression retained well (17.39%, P = 0.001, chi-square test)." (PMID 25938540, 2015). "We also note that Id1 expression in NSCLC cells is largely growth factor dependant and constitutive expression of Id1 in NSCLC cells significantly increases tumor cell migration without affecting cell proliferation." (PMID 20414347, 2010). "As reported, we could confirm robust ID1 protein expression in PDAC, regardless of tumour region and in line with TCGA data." (PMID 40826447, 2025). "We detected the mRNA expression levels of Id-1 and CCN2 in 48 HCCs and their adjacent non-tumor liver tissues, and found increased Id-1 expression in 70.83% (34/48), and increased CCN2 expression in 64.58 (31/48) of HCC tissues compared with the corresponding non-tumor liver tissues." (PMID 31250351, 2019). "TGFb/ID1 signals promote metastatic colonization via a MET, antagonizing TWIST1 EMT in normoxic metastatic sites, but not in hypoxic primary tumor sites, where EMT is governed by SNAIL1." (PMID 30899759, 2019).
tumor (continued). "The prevailing view is that ID1 is downregulated by TGF-β in non-tumorigenic human epithelial lines, but upregulated by TGF-β in established tumor cell lines, as we have observed here in MDA-MB-231 and BT-549s, and also in patient-derived tumor cells." (PMID 29376829, 2018). "Cells expressing Id1 did not demonstrate any notable change in growth versus GFP-expressing cells, and both transduced cell lines were found to grow more slowly than the noninfected tumor cells." (PMID 20414347, 2010). "Transcriptional profiling classified the Ta tumours as luminal (high expression of luminal markers such as GATA3, PPARG, FOXA1 and XBP1 as well as differentiation markers such as UPK1A and KRT20) as well as non-aggressive (high expression of SKAP2, FABP4, MBNL2 and ID1)." (PMID 28916750, 2017). "However, in the presence of extracellular signaling molecules that can induce Id1 but not GCIP expression in NSCLC cell lines (e.g., BMP2), upregulation of Id1 may overcome the tumor suppressive functions of GCIP." (PMID 24970809, 2014). "We found that although Id-1 was again significantly correlated with Gleason grade of individual cores in our cohort (r=0.356, P<0.001), TNF-β did not correlated with either Gleason score of the tumours (r=−0.028, P=0.709) or Gleason grade of the individual cores (r=−0.04, P=0.532)." (PMID 20010941, 2010).
cancer (234 papers, 2004 to 2025). A tumor composed of atypical neoplastic, often pleomorphic cells that invade other tissues. "No Id1 mutations have been found, although numerous reports have linked Id1 to the induction of invasion and metastasis in human cancer through promotion of the epithelial–mesenchymal transition (EMT)." (PMID 41303422, 2025). "ID1 functions as a pivotal transcriptional regulator implicated in various human cancers, including ESCC." (PMID 40652518, 2025). "Known to regulate biological processes such as cell differentiation, proliferation, migration, and angiogenesis, ID1 expression by cancer cells is associated with poor patient prognosis." (PMID 40116596, 2025). "ID1, in particular, is overexpressed in gastric, ovarian, colon, breast, liver, and other cancer cells, and shown to be associated with cell growth, EMT, cell cycle, metabolic reprogramming and with drug resistance." (PMID 39123206, 2024). "ID1 proteins are over-expressed in a variety of tumors, in which over-expression of ID1 was found to be associated with cancer aggressiveness and poor clinical outcomes." (PMID 37373188, 2023). "Secondly, TGFβ can actively exert its oncogenic effect in Smad4-deficient cancers through stabilizing ID1 protein." (PMID 33990575, 2021). "In virtually all of these cancer types the presence of ID1 and/or ID3 is associated with an aggressive phenotype and poor clinical outcome." (PMID 34031428, 2021). "In general, the expression of E6 in cancer cells is associated with overexpression of Fascin, Id-1 and P-cadherin— all of which are actively involved in cell invasion and metastasis." (PMID 32325943, 2020). "Due to its role in cell differentiation, Id-1 has also been implicated in the biology of cancer stem cells." (PMID 31250351, 2019). "ID1 is deregulated in cancer, associated with poor prognosis, and contributes to stem cell phenotype." (PMID 30813586, 2019). "Inhibitor of differentiation 1 (Id1) is the member mostly linked to tumorigenesis in Id family and a potential molecular target in cancer therapy." (PMID 30949224, 2019). "High levels of ID1 are found in human cancers of the breast, lung, and esophagus and are associated with poor patient prognosis." (PMID 31296250, 2019). "Among four types of Id proteins (Id1, Id2, Id3, and Id4), Id1 has been extensively studied in various cancers and is linked to tumorigenesis, as aberrant elevation of Id1 has been found in over 20 types of human cancer." (PMID 24970809, 2014). "Overexpression of ID1 has been described in several cancers and has been specifically linked to increases in VEGFA gene transcription." (PMID 25207642, 2014). "Inhibition of BMP signaling with the selective antagonist DMH2 caused a decrease in the expression of Id1/Id3 and induced significant growth inhibition of cancer cells expressing Oct4 or nestin." (PMID 24160469, 2013). "Together, increased Id1 and Id3 expression is observed in many cancers and is associated with poor prognosis." (PMID 23342268, 2012). "Increased proliferation is a well-established hallmark of cancer cells that is known to be regulated by Id1 and Id3." (PMID 23342268, 2012). "Of all the four Id proteins, the expression of Id1 and Id2 in cancer and the underlying molecular mechanism is relatively well known." (PMID 23342268, 2012). "Of all the four Id proteins, the expression of Id1, Id2, and to a lesser extent, Id3 in cancer and the underlying molecular mechanism is relatively well known." (PMID 23342267, 2012). "Id1 is known to be associated with more invasive features of cancer and with the epithelial-mesenchymal transition (EMT)." (PMID 21955753, 2011). "Taken together, elevated endogenous ID1 expression, as seen in diverse cancer cell lines, is associated with an increased number of centrosome abnormalities." (PMID 20070914, 2010).